BRAF (B-Raf proto-oncogene, serine/threonine kinase)
Diseases named in the same sentence as BRAF in open-access papers (continued):
Sharing a sentence is not in itself a finding about the gene and the disease.
Noonan syndrome (39 papers, 2012 to 2025). "Somatic pathogenic variants in genes of the RAS/MAPK signaling pathway, in turn, are causative for RASopathies such as Noonan syndrome (BRAF, MAP2K1, PTPN11, or RAF1 variants), Costello syndrome (HRAS variants) as well as other Noonan-like syndromes." (PMID 38835734, 2023). "Going further into the signaling cascade, both RIT1 and RAS activate BRAF, heterozygous gain-of-function mutations which result in Noonan syndrome 7 (OMIM: 613706)." (PMID 35806420, 2022). "SOS1 and BRAF are associated with Noonan syndrome, an autosomal‐dominant disorder characterized by short stature, congenital heart disease, curly hair, and facial dysmorphia." (PMID 35505885, 2022). "GS detected a pathogenic heterozygous point mutation NM_004333:c.G1411T(p.V471F) in BRAF gene, which was reported to cause Cardio-Facio-Cutaneous Syndrome and Noonan Syndrome in an autosomal dominant manner." (PMID 31475041, 2019). "Mutations associated with Noonan syndrome alone include CBL, BRAF, KRAS, LZTR1, MAP2K1 (MEK1), NRAS, PTPN11, RAF1, RIT1, SOS1 and SOS2." (PMID 38550930, 2023). "CFC is caused by mutations in BRAF, MEK1 and MEK2; Noonan syndrome by mutations in PTPN11, SOS1, KRAS, RAF1, SHOCK2, NRAS and occasionally BRAF and MEK1; and Costello syndrome by mutations in HRAS4–12." (PMID 33795686, 2021). "Germline BRAF mutations can cause CFC syndrome (approximately 50–75%), Noonan syndrome, and LEOPARD syndrome type 3 (< 2%)." (PMID 30290804, 2018). "Although B-Raf proto-oncogene (BRAF) mutations are associated with cardio-facio-cutaneous (CFC) syndrome and Noonan syndrome, it remains unclear how these mutations impair cognition." (PMID 39964758, 2025). "In addition to the PTPN11 mutations in the RAS‐MAPK signaling pathway, including KRAS, SOS1, RAF1, SHOC2, NRAS, BRAF and CBL, can also cause Noonan syndrome." (PMID 37525886, 2023). "In the absence of SH3BP2 mutation in an individual considered to have Cherubism, genetic screening for mutations in genes implicated in Noonan syndrome (PTPN11, SOS1, RAF1, KRAS, NRAS, and BRAF), NF1, and craniofacial cutaneous syndrome (BRAF, MAP2K1) should be undertaken." (PMID 25409853, 2014). "Mutations in BRAF disrupt the regulation of MAP kinase/ERK pathway and can lead to a range of complications including various types of cancers as well as developmental disorders such as Noonan syndrome (NS), Costello syndrome, LEOPARD syndrome, and Cardiofaciocutaneous syndrome (CFC)." (PMID 29416564, 2018). "Over the years, several other genes involved in Noonan syndrome (KRAS, SOS1, RAF1, MAP2K1, BRAF, NRAS, RIT1, and LZTR1) have been identified, acting at different levels of the RAS-mitogen-activated protein kinase pathway." (PMID 38254922, 2023). "Since fibrous osseous dysplasia has been described in cherubism and sporadically in Noonan syndrome, sequencing of exon 9 of the SH3BP2 or KRAS, BRAF and PTPN11 genes was performed, but no pathogenic variant was detected." (PMID 33685999, 2022). "Gene sets in protein phosphorylation and JUN-MAPK (mitogen-activated protein kinase) cascades were also enriched but not entirely due to three Noonan syndrome genes (PTPN11, BRAF, RAF1)." (PMID 30532227, 2018).
chronic myeloid leukemia (38 papers, 2011 to 2024). "Taking BRAF V600E as an example, we found that in chronic myeloid leukemia, 22% of cells have BRAF V600E mutation, which is consistent with previous research." (PMID 39420637, 2024). "Considering the RAS/MAPK pathway and BCR-ABL1 fusion both play important roles in chronic myeloid leukemia, and BRAF is a key factor of the RAS/MAPK pathway, our findings indicate the diverse patterns of clonal selection and mutual exclusion of driver mutations in chronic myeloid leukemia." (PMID 39420637, 2024). "The results of these tests allow the choice of target therapies specific to each patient (e.g., quantification of BRAF V600 mutations for anti-RAF and anti-MEK target therapies, or BCR-ABL fusion genes for Imatinib treatment in chronic myeloid leukemia or lymphoblastic leukemia acute)." (PMID 36376956, 2022). "It is becoming clear that resistance to BRAF inhibitors will not follow the pathway of resistance of chronic myelogenous leukemia (CML) to imatinib, where secondary mutations in the abl kinase are the main mechanism of resistance." (PMID 22194965, 2011).
colon adenocarcinoma (38 papers, 2011 to 2026). "Lastly, we show primary colon adenocarcinoma patient samples with R117fs and G659fs variants have transcriptional profiles similar to BRAF missense mutations with activated RAS/MAPK signaling, consistent with KRAS signaling pathways being GOF in both variants." (PMID 34214079, 2021). "In order to verify this presumption, we examined the levels of p-NPM1 (Thr199) in tumor tissues from colon adenocarcinoma (CA) patients with different BRAF mutational statuses using immunohistochemistry." (PMID 34201061, 2021). "It is well known that right colonic adenocarcinomas have distinct molecular characteristics with more frequent microsatellite instability and BRAF mutation compared to left colonic adenocarcinomas." (PMID 27124490, 2016). "In particular, 45 adenocarcinomas (41 colon, 2 lung, 2 pancreas) exhibited co-occurring KRAS and PIK3CA mutations; two colon adenocarcinomas had concomitant BRAF and PIK3CA mutations." (PMID 26435479, 2015). "The KRAS and BRAF V600E mutation rates detected in our series by both Sanger sequencing and ASLNAqPCR are compatible with the data reported in the literature for colon adenocarcinoma and the other tumors analyzed." (PMID 22558339, 2012). "Based on these findings, her final diagnosis was adenocarcinoma of the colon with lymph node and liver metastases (cT3N1M1, stage IVc, BRAF-V600E(+), MSS type)." (PMID 39759155, 2024). "Based on pathological and genetic testing, the final diagnosis was colon adenocarcinoma with lymph node and liver metastases (cT3N1M1, stage IVc, BRAF-V600E(+), MSS type)." (PMID 39759155, 2024). "In conclusion, overexpression of BRAF in colon adenocarcinoma is considered a poor prognostic pathological marker." (PMID 36673047, 2023). "The most frequent cancer types with BRAF mutations were THCA (59.3%), SKCM (53.6%), colon adenocarcinoma/rectum adenocarcinoma (COADREAD) (10.6%), LUAD (7.2%) and UCEC (4.7%)." (PMID 35910024, 2022). "The data they collected using cell lines of colon adenocarcinoma shows that BRAF-V600E induces migration and enhances the invasive potential of these cells." (PMID 25157365, 2014). "The overexpression of mutant BRAF in colon adenocarcinoma cells had quite the opposite effect of the anticipated increase in sensitivity to the 17-AAG inhibitor." (PMID 21738740, 2011). "Also, BRAF expression correlated with the pathological stage in colon adenocarcinoma, kidney renal clear cell carcinoma, lung squamous cell carcinoma, and ovarian serous cystadenocarcinoma." (PMID 38919805, 2024). "This is evidenced by the recent finding that BRAF V600E and KRAS G13D mutations in colon adenocarcinoma upregulate the transcription factors MAFG and ZNF304, respectively, resulting in targeted promoter CGI hypermethylation near the MAFG and ZNF304 binding sites." (PMID 32327612, 2020). "Various potential biomarkers have been found in colon adenocarcinoma (COAD) patients receiving immunotherapy, such as microsatellite instability (MSI), programmed cell death-ligand 1 (PD-L1) expression, tumor mutation burden (TMB) and BRAF and KRAS gene mutation status." (PMID 34367132, 2021). "Importantly, we detected significantly stronger nuclear and, in particular, cytoplasmic staining of phospho-NPM1 (Thr199) in tumor tissue specimens from BRAFV600E-mutated in comparison with KRAS mutant/BRAF wild-type and double wild-type KRAS/BRAF colonic adenocarcinomas using immunohistochemistry." (PMID 34201061, 2021). "To determine if MCs were also enriched in BRAF-mutant human CRC, we performed CIBERSORT analysis on The Cancer Genome Atlas (TCGA) colon adenocarcinoma (COAD) patient data." (PMID 41039118, 2025).
colon adenocarcinoma (continued). "In this sense, this study aimed to explore the prognostic utility of BRAF, programmed death-1 (PD1), and its ligand (PDL1) protein signatures in colon adenocarcinoma." (PMID 36673047, 2023). "Linkage between the RhoA-ROCK and the BRAF-ERK-MAPK pathway has previously been described, for example in the control of osteogenic gene expression and in colon adenocarcinoma cells, where it induced cell migration and invasion." (PMID 26828592, 2016). "This study shows for the first time that BRAF and RAS oncogenes utilise different Rho signalling pathways to induce migration and invasion properties in human colon adenocarcinoma cells." (PMID 21943101, 2011). "Combined immunohistochemical assessment for BRAF and PD1/PDL1 protein expressions in colon adenocarcinoma might be beneficial for selecting patients for future targeted therapy." (PMID 36673047, 2023).
mucinous adenocarcinoma (38 papers, 2011 to 2026). An invasive adenocarcinoma composed of malignant glandular cells which contain intracytoplasmic mucin. "Mucinous adenocarcinoma was more common in tumors with BRAF/NRAS mutations (two of six cases, 33.3%) compared with KRAS-mutated tumors (six of 39 cases, 15.4%) or WT tumors (two of 27 cases, 7.4%)." (PMID 41439081, 2025). "Mucinous adenocarcinoma occurred more than twice as frequently in BRAF/NRAS-mutated tumors as in KRAS-mutated tumors, and more than four times as frequently as in WT tumors." (PMID 41439081, 2025). "Mucinous adenocarcinoma was more common in tumors with BRAF/NRAS mutations than in KRAS mutant or WT tumors." (PMID 41439081, 2025). "Key findings include a high frequency of KRAS mutations, a trend linking BRAF/NRAS mutations to mucinous adenocarcinoma, and a significant association between KRAS mutations and older patient age." (PMID 41439081, 2025). "On the contrary, no morphologic patterns were described to be associated with KRAS and BRAF mutations except for mucinous adenocarcinomas, which were associated with a higher probability of BRAF mutation." (PMID 38201408, 2023). "While BRAF mutation was infrequent in MBTs (2%), it was relatively more common in mucinous carcinoma and serous adenoma." (PMID 37600581, 2023). "Mucinous adenocarcinomas, defined as tumors in which >50% of the lesion is composed of extracellular mucus, constitute a distinct histologic subtype and are associated with BRAF mutations, MSI status, and the CpG island methylator phenotype (CIMP)." (PMID 36293565, 2022). "In our results, the BRAF-mutated frequencies were separately 12.62 and 16.98% in TCGA and validation cohort, and higher in the elderly and less in mucinous adenocarcinoma (P < 0.05)." (PMID 33836681, 2021). "One case of appendiceal mucinous adenocarcinoma had BRAF p.V600E mutation and alteration in the RNF43 gene with stable expression of MMR proteins." (PMID 33712927, 2021). "A previous study investigated the clinical and pathological characteristics of CRCs according to BRAF mutation status, and demonstrated a relation between poor prognosis in mucinous tumors, and BRAF gene mutation, as compared to non-mucinous carcinoma." (PMID 34063682, 2021). "According to the TCGA database, BTG1 mRNA expression was lower in well-, moderately, and poorly differentiated than mucinous adenocarcinomas and positively correlated with ras or BRAF mutation (P < 0.05)." (PMID 33330092, 2020). "Further, approximately 75% of BRAF mutation tumors contain a mucinous adenocarcinoma histology, which is more frequent than BRAF wild-type and KRAS/BRAF wild-type tumors." (PMID 30922401, 2019). "BRAF mutations were more frequently observed with right-sided colon, poorly differentiated or mucinous adenocarcinoma, and peritoneal metastasis." (PMID 25886136, 2015). "Location: BRAF mutated tumours are more likely to develop on the right of the colon, and appear as poorly differentiated adenocarcinomas or mucinous carcinomas, as well as with peritoneal metastasis, compared with left side CRC." (PMID 25361007, 2014). "BRAF mutated tumours were more likely to develop on the right of the colon, and to be of the poorly differentiated adenocarcinoma or mucinous carcinoma, and peritoneal metastasis." (PMID 21285991, 2011). "We also found that 60.0% of the BRAF mutation-positive specimens were of the poorly differentiated adenocarcinoma or mucinous carcinoma subtypes." (PMID 21285991, 2011). "Furthermore, BRAF mutations correlated with poorer differentiation and the presence of more aggressive histological subtypes, including mucinous adenocarcinoma." (PMID 39628993, 2024). "In our study, we also proved mucinous adenocarcinoma tended to have BRAF mutation." (PMID 33836681, 2021). "On top of that, BRAF mutations surfaced in all mucinous adenocarcinoma." (PMID 33145020, 2020).
mucinous adenocarcinoma (continued). "Furthermore, 60% BRAF mutation-positive specimens belonged to poorly differentiated adenocarcinoma or mucinous carcinoma subtypes." (PMID 22043994, 2012). "As BRAF mutation was more frequent in mucinous groups than non-mucinous carcinoma, as demonstrated by the present study and others, the poor prognosis associated with mucinous histology may be at least partially explained by BRAF gene mutation." (PMID 21285991, 2011). "Some CRC types, such as high MSI (MSI-H), B-Raf proto-oncogene, serine/threonine kinase (BRAF) mutant, and mucinous adenocarcinoma, depend highly on the TME, making it difficult to construct organoids successfully." (PMID 38983913, 2024). "Our data for both KRAS and BRAF were similar to previously reported rates in mucinous adenocarcinoma, and further stratification indicates similar characteristics of AWMC and AC in each specific location." (PMID 32582557, 2020). "Type I EOCs including low grade serous and mucinous carcinomas are typically Kirsten rat sarcoma viral oncogene homolog (KRAS)- and v-Raf murine sarcoma viral oncogene homolog B (BRAF)-mutated." (PMID 32605254, 2020). "The BRAF V600E mutation is the most common BRAF mutation, of which accounts for approximately 90% cases and it is reported to be associated with features such as proximal location, MSI, and mucinous adenocarcinoma components." (PMID 30922401, 2019). "In accordance with previous reports, BRAF mutant tumors are more likely to develop in the right colon, and to have poorly differentiated or mucinous adenocarcinoma, and peritoneal metastasis in comparison with BRAF wild-type tumors." (PMID 25886136, 2015). "Patients with following characteristics had higher incidence of CIMP(+): female sex, proximal tumor location, mucinous adenocarcinoma histology, MSI-high, and BRAF mutation." (PMID 26157509, 2015). "Similar to CIMP(+), concurrent methylation had higher incidence in patients with proximal tumor location, mucinous adenocarcinoma histology, MSI-high, and BRAF mutation." (PMID 26157509, 2015). "BRAF mutant tumors were more likely to develop in the right colon (57.1 vs. 18.0%, P = 0.001), and to have poorly differentiated or mucinous adenocarcinoma (42.9 vs. 7.2%, P = 0.001), and peritoneal metastasis (50.0 vs. 18.0%, P = 0.009) in comparison with BRAF wild-type tumors." (PMID 25886136, 2015). "Clinicopathological features previously reported to be associated with CIMP positive epigenotype include female sex, older age of diagnosis, proximal colon, poor differentiation, mucinous carcinoma, low frequency of KRAS mutation, and high frequency of BRAF mutation." (PMID 24822060, 2014). "Analysis with respect to histology showed that the frequencies of poorly differentiated adenocarcinoma (por), mucinous carcinoma (muc) and signet-ring cell carcinoma (sig) were <10.9% in patients with wt BRAF, which supported previous reports that such histologies are rare in CRC." (PMID 21285991, 2011). "In contrast, another study found an association between mucinous adenocarcinoma and KRAS mutations, but not with NRAS or BRAF mutations." (PMID 35681771, 2022). "Another study found an association between mucinous adenocarcinoma and KRAS mutations, but not with NRAS or BRAF mutations." (PMID 35681771, 2022).
mucinous adenocarcinoma (continued). "Nkx2-1 deletion in established BRAF-mutant LUAD induces mucinous adenocarcinoma without altering tumor growth." (PMID 33821796, 2021). "Also, there was only 1 BRAF mutation in MBT and no mutation in mucinous carcinomas." (PMID 37600581, 2023).